CAMTA1 (calmodulin binding transcription activator 1)
Description:
Transcriptional activator.
Synonyms: KIAA0833; CANPMR; CECBA
Tractability: Small molecule: it has a binding pocket of medium quality. PROTAC: ubiquitination databases record sites on it.
Gene: Protein-coding gene on chromosome 1 (6,785,454 to 7,769,706, forward strand). Ensembl gene ENSG00000171735.
Subcellular location: Nucleus; Cytoplasm
Subcellular location (Human Protein Atlas): Cytosol; Basal body; Nucleoli
Gene Ontology:
Molecular function: transcription coregulator activity; DNA binding; sequence-specific DNA binding
Biological process: positive regulation of calcineurin-NFAT signaling cascade; regulation of transcription by RNA polymerase II; positive regulation of transcription by RNA polymerase II
Cellular component: cytoplasm; nucleus
Genetic constraint (gnomAD): Loss-of-function variants: 24 observed, 148.77 expected, observed/expected ratio (o/e) 0.16, 90% interval 0.12 to 0.23. The upper end of that interval is the gene's LOEUF score, 0.23, which puts it in group 1 of 6, group 1 being the genes least tolerant of losing a copy. Missense variants: 1,541 observed, 2,146.1 expected, observed/expected ratio (o/e) 0.72, 90% interval 0.69 to 0.75. Synonymous variants: 786 observed, 871.15 expected, observed/expected ratio (o/e) 0.9, 90% interval 0.85 to 0.96.
Gene-disease validity (ClinGen):
ClinGen rates the evidence that CAMTA1 causes each of these diseases.
cerebellar dysfunction with variable cognitive and behavioral abnormalities (autosomal dominant): Definitive.
Cancer hallmarks: suppression of growth (promotes)
Homologues: Orthologues: chimpanzee CAMTA1 (99% identical), macaque CAMTA1 (99% identical), dog CAMTA1 (96% identical), mouse Camta1 (94% identical), rat Camta1 (94% identical), pig CAMTA1 (94% identical), guinea pig CAMTA1 (93% identical), rabbit CAMTA1 (90% identical), tropical clawed frog camta1 (77% identical), zebrafish camta1a (65% identical), zebrafish camta1b (58% identical). Paralogues in human: CAMTA2 (39% identical).
Diseases named in the same sentence as CAMTA1 in open-access papers:
CAMTA1 is named in the same sentence as 73 diseases in open-access papers, as found by Europe PMC text mining. Sharing a sentence is not in itself a finding about the gene and the disease. The quoted sentences say what the papers report.
epithelioid hemangioendothelioma (33 papers, 2013 to 2025). A low-grade malignant blood vessel neoplasm. "For example, in 2011 a rare vascular sarcoma called epithelioid hemangioendothelioma was found to have a WWTR1/CAMTA1 gene fusion and a specific diagnostic fluorescent in situ hybridisation assay for this translocation was devised." (PMID 24216705, 2013). "One such fusion protein, YAP-TFE3, occurs in 10 to 20% of epithelioid hemangioendotheliomas, a vascular tumor that is caused by fusion of the N terminus of either YAP or TAZ with TFE3 or CAMTA1, respectively." (PMID 40712036, 2025). "TAZ::CAMTA1 is a fusion protein found in over 90% of Epithelioid Hemangioendothelioma (EHE), a rare vascular sarcoma with an unpredictable disease course." (PMID 37980390, 2023). "In one study, all angiosarcomas were negative for CAMTA1, allowing for the distinction between angiosarcomas and epithelioid hemangioendotheliomas, of which 90% of cases were positive for CAMTA1." (PMID 37510144, 2023). "Genetic studies of the WWTR1 (a protein known as TAZ)-CAMTA1 were well established in epithelioid hemangioendothelioma (EHE), a malignant vascular cancer." (PMID 36159397, 2022). "Remarkably, gene fusion of WWTR1-CAMTA1 (calmodulin-binding transcription activator 1) happens in virtually all epithelioid hemangioendothelioma." (PMID 27412635, 2016). "Recent studies showed that the TAZ gene is frequently fused with calmodulin-binding transcription activator 1 (CAMTA1) in epithelioid hemangioendothelioma, although the function of this fusion protein in cancer is still unclear." (PMID 26375055, 2015). "CAMTA1 is a highly sensitive and specific diagnostic marker and can help distinguish EHE with WWTR1::CAMTA1 fusion from cellular epithelioid hemangiomas and epithelioid angiosarcomas." (PMID 36983010, 2023). "Interestingly, these fusions lead to the mutually exclusive nuclear accumulation of CAMTA1 or TFE3, making IHC a reliable read out for both variants of epithelioid hemangioendothelioma." (PMID 33114111, 2020). "Recently, a YAP and transcription factor E3 (TFE3) (YAP-TFE3) fusion gene, and a TAZ and calmodulin-binding transcription activator 1 (CAMTA1) (TAZ-CAMTA1) fusion gene were reported in cases of epithelioid hemangioendothelioma, a rare type of soft tissue sarcoma." (PMID 31100975, 2019). "A primary endovascular EHE pulmonary endovascular epithelioid hemangioendothelioma was diagnosed by endovascular biopsy with positive stains for molecular CD31, CD34 and CAMTA1, and it had low proliferative capacity characterized by Ki-67 of 5%." (PMID 36800635, 2023). "Some epithelioid hemangioendothelioma demonstrate a fusion of WWTR1 and CAMTA1CAMTA1, and immunohistochemistry for CAMTA1 can be positive, while others with YAP1-TFE3 fusion show nuclear expression of TFE3." (PMID 37510144, 2023). "Herein, we present a unique TAZ-driven cancer, epithelioid hemangioendothelioma (EHE), which harbors a WWTR1(TAZ)–CAMTA1 gene fusion in at least 90% of cases." (PMID 35740643, 2022). "Immunohistochemical staining of CAMTA1 can help the differentiation of EHE and epithelioid angiosarcoma." (PMID 36083389, 2022). "Epithelioid angiosarcomas show more cytologic atypia than epithelioid hemangioendotheliomas and are negative for CAMTA1." (PMID 32316685, 2020). "Importantly, strong immunopositivity for CAMTA1 is expressed mainly in EHE and not in the EHE cases that mimic other vascular tumors like epithelioid angiosarcoma and epithelioid sarcoma, highlighting its importance as a diagnostic marker for EHE." (PMID 39650162, 2024).
Ataxia (8 papers, 2016 to 2025). Ataxia refers to impaired coordination of voluntary muscle movement. "Just a few studies reported that the CAMTA1 gene had been associated with neonatal neuroblastoma, ataxia, and sporadic amyotrophic lateral sclerosis." (PMID 36159397, 2022). "Loss of CAMTA1 in the mouse nervous system leads to defects in hippocampal-dependent memory formation, degeneration of cerebellar Purkinje cells and ataxia." (PMID 34499028, 2021). "CANPMR syndrome (OMIM 614756) is a rare genetic disorder of the nervous system presenting with cerebellar ataxia and mild to severe mental retardation, whose genetic cause was recently described to be CAMTA1 haploinsufficiency." (PMID 26848311, 2016). "Interestingly, haploinsufficiency in CAMTA1, a member of the calmodulin-binding transcription activators, results in early-onset ataxia in humans, and nervous system deletion of CAMTA1 in mice causes severe ataxia with Purkinje cell degeneration and cerebellar atrophy." (PMID 34227061, 2021). "Humans heterozygous for lesions in the CAMTA1 gene exhibit a range of neurological phenotypes, including intellectual disability, cerebellar ataxia, and reduced memory performance." (PMID 34499028, 2021). "Studies have shown that CAMTA1 KO mice could develop ataxia, Purkinje fibrosis, and other characteristics." (PMID 36159397, 2022). "Mice lacking the CAMTA1 (calmodulin-binding transcription activator 1) transcription factor had shown severe ataxia and Purkinje cell degeneration." (PMID 36614124, 2022). "Mice lacking Camta1 develop ataxia and show Purkinje cell degeneration along with significant cerebellar atrophy at the age of 3 months." (PMID 30357366, 2019).
glioblastoma (8 papers, 2012 to 2024). The most malignant astrocytic tumor (WHO grade IV). "On the contrary, Schraivogel D suggested that miR-9 was highly abundant and negatively regulated tumor suppressor CAMTA1 in the glioblastoma stem cells." (PMID 30795814, 2019). "Surprisingly, CAMTA1 was identified as a tumor suppressor in glioblastoma cancer stem cells, while JAK-STAT signaling was reported to promote gliomagenesis." (PMID 23185366, 2012). "However, one study has reported that miR-9-3p regulates expression of calmodulin-binding transcription activator 1 (CAMTA1) in CD133+ glioblastoma stem cells." (PMID 28430789, 2017). "In glioblastoma cells, overexpression of miR-9/9* could inhibit the expression of the tumor suppressor gene CAMTA1, leading to enhanced cell survival, implying that it might be an oncomir." (PMID 24373626, 2013). "The studies so far raise interesting questions about why some fusion proteins seem to be specific to a particular disease, such as TAZ::CAMTA1 to EHE, whereas others are more permissive across a range of tumors, such as YAP::MAML2 to poroma, metaplastic thymoma, and glioblastoma, among others." (PMID 40491864, 2024). "In glioblastoma, lncRNA RBPMS-AS1 downregulate radioresistance via miR-301a-3p/CAMTA1 axis." (PMID 35600868, 2022).
glioma (7 papers, 2011 to 2023). A benign or malignant brain and spinal cord tumor that arises from glial cells (astrocytes, oligodendrocytes, ependymal cells). "Calmodulin binding transcription activator 1 (CAMTA1), a key member of this transcription factor family, is also a tumor suppressor, inhibiting the growth of a variety of cancers, including glioma and colon cancer." (PMID 35332122, 2022). "CAMTA1 is a tumor suppressor candidate found to inhibit growth in neuroblastomas and appears to play a role in the development of glioma stem cells." (PMID 26039411, 2015). "Moreover, the RBPMS-AS1 and CAMTA1 expression levels were decreased in glioma tissues and cells." (PMID 36544782, 2022). "Meanwhile, Calmodulin Binding Transcription Activator 1 (CAMTA1) plays a vital role in the human nervous system and affects the prognosis of glioma." (PMID 36980973, 2023). "In addition to CREB and NF1, previously established targets of miR-9 in glioma stem cells, such as CAMTA1 and JAK1/2, might contribute to the function of miR-9 in glioma cells, although further investigation will be required." (PMID 23185366, 2012).
vascular tumors (7 papers, 2022 to 2025). "Furthermore, CAMTA1 is a highly-sensitive biomarker that has been used in the differential diagnosis of hepatic epithelioid hemangioendothelioma and angiosarcoma, two vascular tumor types, and low CAMTA1 expression has been associated with poor prognosis in colorectal cancer." (PMID 35332122, 2022). "For instance, we showed that genetic inactivation of the TAZ::CAMTA1–TEAD signaling axis by overexpression of a dominant-negative TEAD2 could completely prevent the formation of TAZ::CAMTA1-dependent EHE-like vascular tumors in mice." (PMID 40491864, 2024). "Expression of CAMTA1 is highly specific for EHE and helps differentiate it from other epithelioid vascular tumors." (PMID 40895865, 2025).
angiosarcoma (6 papers, 2022 to 2025). A malignant tumor arising from the endothelial cells of the blood vessels. "EHEs have a distinct myxohyaline stroma and positivity for CAMTA1, and lack the well-developed vasoformation seen in angiosarcoma." (PMID 40002892, 2025). "Epithelioid angiosarcomas have more significant nuclear atypia and frequent mitoses, and they are negative for CAMTA1." (PMID 40002892, 2025). "Therefore, a genetic evaluation was requested for clarification, revealing a negative result for the WW domain-containing transcription regulator protein 1 - calmodulin binding transcription activator 1 (WWTR1-CAMTA1) fusion gene, validating the diagnosis of an angiosarcoma." (PMID 39734979, 2024). "Although EHE expresses similar molecular markers to angiosarcoma (CD31, CD34, and ERG), angiosarcoma differs greatly from EHE in terms of light microscopy morphology and often exhibits MYC amplification without CAMTA1/TFE3 expression." (PMID 40896782, 2025). "However, biopsy results that are positive with IHK CD31, ERG, and negative with IHK AE1, CAMTA1, and TFE can confirm the diagnosis of angiosarcoma." (PMID 39142183, 2024).
neuroblastoma (6 papers, 2010 to 2022). Neuroblastoma (NB) is the most common solid, extracranial childhood tumor. "CAMTA1, which is deleted in neuroblastoma, induces neurites and expression of neuronal differentiation markers." (PMID 29354032, 2017). "Another tumor suppressor regulated by miR-34a was CAMTA1, a reduction in whose levels correlates with poor outcome in neuroblastoma." (PMID 20420713, 2010). "CAMTA1 gene was identified in 2003 as a candidate for tumor suppressor in neuroblastoma." (PMID 36159397, 2022). "Moreover, CAMTA1 was studied in neuroblastoma cells, where it slowed cell proliferation and induced neurite-like processes by activating the markers of neuronal differentiation." (PMID 32784482, 2020). "However, a large number of genes located within the 1p36 region have been proposed as tumor suppressors in neuroblastoma and other tumors, including CHD5, CAMTA1, miRNA-34a, CASZ1, KIF1B, and the HES gene family." (PMID 27014418, 2016).
soft tissue sarcoma (4 papers, 2019 to 2025). A malignant neoplasm arising from muscle tissue, adipose tissue, blood vessels, fibrous tissue, or other supportive tissues excluding the bones. "EHE is a soft-tissue sarcoma caused by the fusion of TAZ and calmodulin-binding transcription activator 1 (CAMTA1)." (PMID 34022224, 2021).
Intellectual disability (3 papers, 2019 to 2022). "Genes containing the largest number of DMLs included calmodulin-binding transcription activator 1 (Camta1), which is involved in long-term and episodic memory and has been correlated with intellectual disability when mutated." (PMID 33407853, 2021). "Mutations and intragenic rearrangements in the CAMTA1 gene result in non-progressive cerebellar ataxia with or without intellectual disability and attention deficit hyperactivity disorder (ADHD) in humans." (PMID 36614124, 2022).
periodontitis (3 papers, 2023 to 2024). An acute or chronic inflammatory process that affects the tissues that surround and support the teeth. "Interestingly, gene variants in CAMTA1/VAMP3 have been suspected to be responsible for shared predisposition to both periodontitis and cardiovascular disease, which is relevant considering the nature of the present sample (MetS)." (PMID 38068972, 2023). "Specific SNPs within RUNX2, CAMTA1 and VDR genes were associated with diversity metrics with no genome-wide associations detected for periodontitis severity or Mets components at p < 10−7." (PMID 38068972, 2023).
thymoma (3 papers, 2016 to 2022). A neoplasm arising from the epithelial cells of the thymus. "To determine the physiological significance of miR-20b targeting NFAT5 and CAMTA1, we assessed the expression levels of miR-20b, NFAT5, and CAMTA1 in thymoma tissue specimens from 30 thymoma-associated myasthenia gravis patients." (PMID 27833920, 2016). "Similarly, miRNA-20b was found to be down-regulated in patients with thymoma-associated MG and to target Nuclear Factor of Activated T-cells 5 (NFAT5) and Calmodulin Binding Transcription Activator 1 (CAMTA1), thus inhibiting T-cell proliferation and activation." (PMID 35409405, 2022). "The tumor suppressive function of miR-20b in thymoma could be due to its inhibition of NFAT signaling by repression of NFAT5 and CAMTA1 expression." (PMID 27833920, 2016).
developmental delay (2 papers, 2016 to 2025). "When the haplodose of CAMTA1 is insufficient, the deletion or duplication of the gene region encoding the CG‐1 domain will affect the function of CAMTA1, resulting in cerebellar abnormalities, ventricle enlargement, with or without related hydrocephalus, and developmental delay." (PMID 40285432, 2025).
ischemic stroke (2 papers, 2022 to 2025). A stroke disorder caused by obstruction of blood flow to the brain, due to thrombotic (local blood clot formation) or embolic (due to a blood clot or other material traveling from another site) event. "We found elevated methylation levels in the promoter region of the CAMTA1 gene in ischemic stroke patients, at the same time with decreased CAMTA1 mRNA expression." (PMID 36159397, 2022). "It suggests that the hypermethylation of the CAMTA1 gene promoter might relate to ischemic stroke." (PMID 36159397, 2022).
liver cancer (2 papers, 2016 to 2017). An epithelial or non-epithelial malignant neoplasm that arises from the liver. "The essential oncogenic role of lncRNA CAMTA1 in liver cancer was further supported by the finding that patients with higher levels of lncRNA CAMTA1 have shorter survival and an increased rate of early recurrence." (PMID 29061150, 2017).
cardiomyopathies (1 paper, 2023). "In particular, Males Only DMRs selected by machine learning feature selection were able to distinguish CHD from non-CHD samples and frequently mapped to genes associated with CHDs or cardiomyopathies, including FUNDC1, ETV5, SYT9, CAMTA1, GRIA4, and IGF1R." (PMID 37803336, 2023).